IGF2R (insulin like growth factor 2 receptor)
Diseases named in the same sentence as IGF2R in open-access papers (continued):
Sharing a sentence is not in itself a finding about the gene and the disease.
cutaneous melanoma (2 papers, 2020 to 2021). A primary melanoma arising from atypical melanocytes in the skin. "It has been reported that IGF2R as a target gene of miR-211 activates the MAPK signaling pathway and thereby inhibits the formation of skin melanoma." (PMID 33117415, 2020).
gastric cancer (2 papers, 2025 to 2026). A primary or metastatic malignant neoplasm involving the stomach. "The four prioritized mutations (PTPRK, PIK3CB, LRP1B, and IGF2R) provide new insights into the genetic landscape of gastric cancer and represent promising candidates for the development of targeted therapeutic strategies." (PMID 41696640, 2026).
liver fibrosis (2 papers, 2023 to 2025). "As the biomarker on the activated hepatic stellate cells (HSCs) for liver fibrosis, IGF2R-targeting peptides have also been developed as the ligand for HSC-related drug delivery." (PMID 39861756, 2025). "In vivo biodistribution studies of the siRNA-aptamer chimera revealed high and specific liver uptake in rats with CCl4-induced liver fibrosis, demonstrating its ability to transport biomolecule drugs by targeting IGF2R." (PMID 39861756, 2025). "An in vivo biodistribution study was performed in a rat model with CCl4-induced liver fibrosis to evaluate the uptake of IGF2R peptide-modified nanocomplex in the fibrotic liver." (PMID 36979383, 2023). "The dimeric IGF2R peptide ligand-modified siRNA nanocomplex with the highest cellular uptake and the most efficient silencing activity was evaluated for its biodistribution in rats with CCl4-induced liver fibrosis." (PMID 36979383, 2023). "In accordance with the literature, the IGF2R-3GK6E peptide-modified nanocomplex demonstrated a significant uptake in the liver, prolonged the half-life of siRNA, and reduced renal clearance, making it a promising siRNA delivery system for the treatment of liver fibrosis." (PMID 36979383, 2023). "Based on the results of the cellular uptake of the dimeric IGF2R peptide-modified nanocomplex in HSC-T6 cells, we next examined the biodistribution of the nanocomplexes in rats with CCl4-induced liver fibrosis." (PMID 36979383, 2023).
lung adenocarcinoma (2 papers, 2022 to 2026). A carcinoma that arises from the lung and is characterized by the presence of malignant glandular epithelial cells. "Another study has demonstrated that IGF2R overexpression enhanced the suppressive effect of irradiation on cancer cell viability and invasiveness in lung adenocarcinoma cells, whereas this effect was attenuated by IGF2R knockdown." (PMID 36299463, 2022).
medulloblastoma (2 papers, 2019 to 2024). A malignant, invasive embryonal neoplasm arising from the cerebellum. "In addition, miR-204 downregulates M6PR, IGF2R genes involved in the lysosomal segregation of cathepsin B and cathepsin D lysosomal enzymes in medulloblastoma cells." (PMID 38611021, 2024). "Furthermore, downregulation of IGF2R protein levels upon miR-204 expression was confirmed by the western blotting in all the three medulloblastoma cell lines." (PMID 30944042, 2019). "MiR-204 expression in medulloblastoma cells resulted in downregulation of both M6PR and IGF2R that mediate transport of lysosomal enzymes from the Golgi apparatus to lysosomes." (PMID 30944042, 2019).
oligodendroglioma (2 papers, 2017 to 2025). A well-differentiated (WHO grade II), diffusely infiltrating neuroglial tumor, typically located in the cerebral hemispheres. "Significant increases in IGF2R were observed in diffuse and anaplastic astrocytomas and oligodendrogliomas, increased PDCD6IP in diffuse and anaplastic astrocytomas, and increased ANXA1 in anaplastic astrocytomas relative to normal brain." (PMID 27770278, 2017).
ovarian tumor (2 papers, 2012 to 2024). "We recently showed that LOH proximal to M6P/IGF2R locus (D6S1581) in primary ovarian tumors is predictive for the presence of disseminated tumor cells (DTC) in the bone marrow (BM)." (PMID 22849543, 2012).
pancreatic cancer (2 papers, 2014 to 2018). "IGF-2R mRNA and protein levels were previously shown to be upregulated in human pancreatic cancer tissues, particuarly in the nucleus of ductal-like pancreatic cancer cells, when compared to the normal pancreatic tissue." (PMID 29475434, 2018).
periodontitis (2 papers, 2020 to 2022). An acute or chronic inflammatory process that affects the tissues that surround and support the teeth. "Interestingly, both IGF2R and HLA-DOA have never been investigated in periodontal medicine, though these potential interactions mainly in the lysocytic/endocytic pathways should be investigated in regard to the interplay between PD and periodontitis." (PMID 33238395, 2020).
rectal cancer (2 papers, 2010 to 2025). A primary or metastatic malignant neoplasm that affects the rectum. "IGF2R exhibited a high mutation frequency in both colon and rectal cancers, with the majority of mutations being missense mutations." (PMID 40426913, 2025). "In rectal MSI-H carcinomas of the test series, we detected mutations only in IGF2R and BAX genes, possible indicating that they are also target genes in the MSI pathway in rectal cancer." (PMID 20979647, 2010).
renal carcinoma (2 papers, 2012 to 2019). A carcinoma arising from the epithelium of the renal parenchyma or the renal pelvis. "Moreover, evidence has been provided that the anti-invasive properties of M6P/IGF2R in renal carcinoma cells are based on downregulation of cell-mediated plasminogen activation." (PMID 22521359, 2012).
alcohol dependence (1 paper, 2015). Physical and psychological dependence on alcohol. "Alcohol dependence was associated with lower CSF IGF2R (β coefficient = −0.35, P = 0.049)." (PMID 25890304, 2015).
chondrosarcoma (1 paper, 2016). A malignant cartilaginous matrix-producing mesenchymal neoplasm arising from the bone and soft tissue. "Heterogeneous expression of IGF1R, IR, IGF2R, IGF1, IGF2, IRS1 and IGFBP3 was seen, both at the mRNA and protein levels, in chondrosarcoma cell lines." (PMID 27418340, 2016).
colitis (1 paper, 2022). Inflammation of the colon. "It has been found that IGF2 in low dose acts through IGF2R and alleviates colitis via promoting anti-inflammatory macrophages, suggesting that IGF2 family strongly controls generation of anti-inflammatory macrophages and may provide novel strategies for the treatment of inflammatory diseases." (PMID 35378790, 2022).
colon cancer (1 paper, 2016). "Analysis of The Cancer Genome Atlas (TCGA) data set suggested that this level of overexpression is unlikely for IGF2R in ovarian, breast, and colon cancer." (PMID 26861122, 2016).
depression (1 paper, 2024). "Expressions of SOD1, CAT, IGF2 and IGF2R also decreased in the postmortem brain regions of individuals with AD and depression compared those of AD, suggesting that the stress-related disorder of depression is indeed a risk factor for AD and exaggerates OS." (PMID 38338968, 2024).
Duchenne muscular dystrophy (1 paper, 2020). Duchenne muscular dystrophy (DMD) is a neuromuscular disease characterized by rapidly progressive muscle weakness and wasting due to degeneration of skeletal, smooth and cardiac muscle. "IGF2R is over‐expressed in Duchenne Muscular Dystrophy (DMD) and mdx muscles." (PMID 31793167, 2020).
encephalitis (1 paper, 2015). An acute inflammatory process affecting the brain parenchyma. "This is consistent with our previous study which showed that de novo IGF2R induction in microglia is found in HIV encephalitis but not in most HIV+ (but HIVE-) brains." (PMID 25890304, 2015).
Ewing sarcoma (1 paper, 2011). A small round cell tumor that lacks morphologic, immunohistochemical, and electron microscopic evidence of neuroectodermal differentiation. "IGF-2R acts as a classic tumor suppressor gene in several different types of cancer, but its relevance in Ewing's sarcoma is unknown." (PMID 22022506, 2011).
gynecological cancers (1 paper, 2019). "Since the present RNAseq data analysis showed high IGF2R expression to be associated with poor prognosis in some gynecological cancers, further studies will be needed to elucidate the oncogenic function of IGF2R in these cancers." (PMID 31748500, 2019).
HCMV infection (1 paper, 2020). "It is possible that IGF2R trafficking to the assembly complex during HCMV infection positions it to facilitate the maturation of HCMV glycoproteins." (PMID 32041945, 2020). "IGF2R was reported to support the replication of the gamma herpesvirus HHV-8 and the retrovirus HIV-188,89, and our results also establish it as a pro-viral factor during HCMV infection." (PMID 32041945, 2020).
head and neck cancer (1 paper, 2011). A primary or metastatic malignant neoplasm affecting the head and neck. "IGF-2R gene status has also been used to determine the course of treatment in head and neck cancer." (PMID 22022506, 2011).
hepatitis C (1 paper, 2018). "Additionally, multiple regression model analyses showed that the presence of the IGF-2R AA or AG genotypes may exert a protective effect against hepatitis C [odds ratio (OR) = 0.35, 95% confidence interval (CI) = 0.15–0.82]." (PMID 30249230, 2018).
herpes simplex (1 paper, 2004). "Indeed, Igf2r has been implicated in herpes simplex and zoster virus infection." (PMID 15333144, 2004).
HIV encephalitis (1 paper, 2015). "IGF2R that is normally expressed by neurons alone in the CNS is highly upregulated in microglia in HIV encephalitis and functions as a cofactor for HIV infection." (PMID 25890304, 2015). "Furthermore, as IGF2R is a scavenging receptor for both IGFs, upregulated IGF2R expression in CSF/CNS (in HIV encephalitis, for instance) could function as a significant modulator of IGF protein expression." (PMID 25890304, 2015).
HIV-associated neurocognitive disorder (1 paper, 2015). HIV-associated neurocognitive disorder (HAND) remains a common complication of HIV infection in the combination antiretroviral therapy (ART) era. "We also determined whether IGF1 or IGF2 deficiency is associated with HIV-associated neurocognitive disorder (HAND) and whether the levels of soluble IGF2R (an IGF scavenging receptor, which we also have found to be a cofactor for HIV infection in vitro) correlate with HIV viral load (VL)." (PMID 25890304, 2015).
Hyperinsulinemia (1 paper, 2024). An increased concentration of insulin in the blood. "Since T1DM is different from the in obese and T2DM, especially considering the hyperinsulinemia, thus the antiatrophy ability of A. muciniphila may be dependent on the recovery of insulin signaling in muscle, evidenced by increased expression levels of Igf2r and Igf2bp1." (PMID 39429872, 2024).
leukemia (1 paper, 2024). A malignant (clonal) hematologic disorder, involving hematopoietic stem cells and characterized by the presence of primitive or atypical myeloid or lymphoid cells in the bone marrow and the blood. "Critically, differential dependency on the Igf2/Igf2r and Fn1/VLA-4 axes upon initiation of fetal- and adult-origin MLLr leukemia may represent an opportunity for targeting ontogeny-specific vulnerabilities in in utero-derived and adult-onset leukemia." (PMID 38555405, 2024).
Lynch syndrome (1 paper, 2025). An autosomal dominant hereditary neoplastic syndrome characterized by the development of colorectal carcinoma and a high risk of developing endometrial carcinoma, gastric carcinoma, ovarian carcinoma, renal pelvis carcinoma, and small intestinal carcinoma. "Of note, this Igf2r indel was also found in one of our Lynch Syndrome CRC patients." (PMID 41256707, 2025). "As the Igf2r indel was also identified in one of our Lynch Syndrome MMRd CRC patients, we determined whether the patient developed ex vivo spontaneous endogenous immunity towards neoepitopes encoded by this indel." (PMID 41256707, 2025). "Of note, one of the MMRd associated indel mutations that we identified (within the Igf2r gene) and predicted candidate neoantigens were found in one of our Lynch CRC patient, and one other (Chrnb2) and associated candidate neoantigens were also found in a murine model of Lynch syndrome." (PMID 41256707, 2025).
memory impairment (1 paper, 2020). "Memory impairment was however already significant at 1 hr after training, indicating that CIM6P/IGF2R is controlling a rapid post-training function that is key for memory consolidation." (PMID 32369018, 2020). "However, once engaged by learning, the function of CIM6P/IGF2R in memory consolidation continued for several hours: only a prolonged post-training blockade of the receptor by two injections, one immediately after training and another 8 hr later, produced memory impairment." (PMID 32369018, 2020).
metastatic melanoma (1 paper, 2024). A melanoma that has spread from its primary site to another anatomic site. "CAFs facilitate the progression from primary to metastatic melanoma and promote proliferation, which is associated with reduced levels of IGF2R (insulin growth factor 2 receptor)." (PMID 39409187, 2024).
morbid obesity (1 paper, 2019). An excess of body weight, normally defined as an individual with a body mass index greater than 35 or a body weight greater than one hundred percent of ideal body weight. "IGF-2R is up-regulated in morbid obesity, down-regulated by weight loss and elevated in moderately obese T2DM, suggesting that IGF-2R is nutritionally regulated, independently of IGF-II." (PMID 30392760, 2019).
Mucopolysaccharidosis VI (1 paper, 2025). "The relationship between IGF2R and endosomal uptake provides an avenue for exogenous ARSB-initiated intracellular effects, as evident in the treatment of Mucopolysaccharidosis VI by replacement therapy with exogenous ARSB." (PMID 40562100, 2025).
muscular dystrophy (1 paper, 2020). Muscular dystrophy (MD) refers to a group of more than 30 genetic diseases characterized by progressive weakness and degeneration of the skeletal muscles that control movement. "To study the effects of IGF2R blockade on muscular dystrophy, we intravenously administered anti‐IGF2R antibodies at low (10 μg per mouse) and high (100 μg per mouse) dosages to 3‐month‐old mdx mice for 4 and 9 weeks." (PMID 31793167, 2020).
Myocardial fibrosis (1 paper, 2022). "IGF-2/IGF-2R can also increase plasminogen activator (PA) expression to promote the occurrence of myocardial fibrosis through disrupting the balance of MMP-9/TIMP-2 expression." (PMID 36358907, 2022). "IGF-2 analog [Leu27]IGF-2 can specifically activate IGF-2R, and the transfection of [Leu27]IGF-2 into rat cardiomyocytes by adenovirus can induce reconstruction characterized by pathological hypertrophy, myocardial fibrosis, and cardiomyocytes’ apoptosis accompanied by massive collagen deposition." (PMID 36358907, 2022).
myopia (1 paper, 2023). "Further analysis using an insulin microarray resulted that the levels of insulin and those related factors including IGF2, IGF-2R, IGF binding protein 1 (IGFBP-1), IGFBP-2, IGFBP-3, IGFBP-4 and IGFBP-6 were markedly increased in patients with pathogenic myopia as compared with the controls." (PMID 38203671, 2023).
non-small cell lung carcinoma (1 paper, 2012). A group of at least three distinct histological types of lung cancer, including non-small cell squamous cell carcinoma, adenocarcinoma, and large cell carcinoma. "The aim of this study is to investigate the relationship of IGF-1R+1013(G/A) and IGF-2R+1619(G/A) single nucleotide polymorphism (SNP) with platinum-based chemotherapy outcomes in advanced non-small cell lung cancer (NSCLC)." (PMID 22336232, 2012).
oral cancer (1 paper, 2025). "In Taiwan population, WES using multiple pipelines of mutant calling has revealed somatic mutation of IGF2R in oral cancer." (PMID 40457841, 2025).
Silver-Russell syndrome (1 paper, 2017). Silver-Russell syndrome is characterized by growth retardation with antenatal onset, characteristic facies and limb asymmetry. "Defects in methylation at ZAC1 and IGF2R have been found in patients with the imprinted disorders transient neonatal diabetes mellitus (TNDM) or Silver-Russell syndrome (SRS), respectively, including those born following the use of ART." (PMID 28134613, 2017).
Temple syndrome (1 paper, 2017). "In addition to the differentially methylated regions on chromosomes 7, 11, and 14 which are affected in the imprinting disorders SRS and Temple syndrome, imprinted loci (PLAGL1, IGF2R) on chromosome 6 were investigated in all these cases as well." (PMID 29178649, 2017).
Wilms’ tumours (1 paper, 2018). "In humans, adult tissues lack IGF2R imprinted expression, but it is found in foetal tissues, placenta, cultured amniotic cells, lymphoblastoid cells and Wilms’ tumours where it is polymorphic." (PMID 30268152, 2018). "The human IGF2R intronic CpG island has promoter activity, and the human orthologue of Airn is present at least in Wilms’ tumours." (PMID 30268152, 2018).